BRAF (B-Raf proto-oncogene, serine/threonine kinase)
Diseases named in the same sentence as BRAF in open-access papers (continued):
Sharing a sentence is not in itself a finding about the gene and the disease.
cancer (continued). "Through integrative bioinformatic analysis of The Cancer Genome Atlas (TCGA) dataset and validation using the Loma Linda University (LLU) patient cohort, we demonstrated that ITGB1, TIMP3, and BRAF function as key molecular determinants of SOC prognosis." (PMID 41294900, 2025). "In this study, we demonstrated that MCs are enriched in BRAF mutant CRC, likely because they are recruited by factors released from cancer secretory cells." (PMID 41039118, 2025). "In BRAF-positive cancers, key genes involved in iodine uptake and metabolism are downregulated, consistent with the higher frequency of radioactive iodine resistant (RAIR) BRAF-positive metastatic lesions." (PMID 39336882, 2024). "These developments have paved the way for the utilization of targeted therapies, including BRAF/MEK inhibitors, for specific genetic alterations across various cancers." (PMID 38203795, 2024). "These are alterations in the BRAF gene, alterations in the KIT gene, rearrangements of the antigen receptor genes, and alterations in panels of known cancer genes." (PMID 38787171, 2024). "Introducing inhibitors targeting BRAF and MAPK Kinase (MEK), crucial components of this pathway, marked a significant breakthrough in treating this cancer." (PMID 39582535, 2024). "BRAF and MEK inhibitors have been developed for the treatment of various types of cancers due to their inhibition of the MAPK pathway and subsequent inhibition of cancer growth." (PMID 38203795, 2024). "Failure of the treatment or acquired resistance are in part attributable to intratumoral heterogeneity not only of cancer cells but of TME populations, particularly in response to BRAF and anti-PD1 therapy." (PMID 39457009, 2024). "Importantly, the use of single-agent BRAF inhibitors significantly elevated the risk of developing cSCC compared to dual BRAF/MEK inhibitors, with a substantial risk increase observed for both all-grade (RR 4.72, 95% CI: 2.42–9.20) and high-grade (RR 4.92, 95% CI: 2.64–9.16) cSCC in cancer patients." (PMID 38893081, 2024). "Over the past three decades, several paradigm-shifting therapeutics have been developed for the treatment of cancer, including immune checkpoint inhibitors (ICIs), BRAF and MEK targeted therapies, and cancer vaccines." (PMID 39451258, 2024). "Given the supportive role of CD8+ T cells in cancer immunotherapy, a decline in CD8+ T-cell signatures, as found in a cohort of patients with cutaneous metastatic melanoma, whose collective incidence of tumoral BRAF mutations was 21.3%, could independently act as a barrier to immunotherapy." (PMID 39336897, 2024). "These DNA targets consisted of multiple KRAS, BRAF and NRAS SNPs, which are commonly used as cancer markers for the detection and characterization of various cancer types, for example, in liquid biopsies." (PMID 39201654, 2024). "An ongoing phase I clinical trial (NCT05501912) is evaluating the efficacy and anti-cancer activity of ABM-1310, a highly potent and selective BRAF inhibitor, in patients with BRAF V600-mutant advanced solid tumors, including CCA." (PMID 39766138, 2024). "BRAF inhibitors such as sorafenib also bind to the kinase domain of BRAF (PDB ID:1UWH) and if these drugs also act as BRAF inhibitors or disrupt the BRAF-RAF1 protein interface, they can be potential anti-cancer drugs." (PMID 38216592, 2024). "Enriched gains spanned known cancer and TGCT drivers including MYC (8q11-q24), EGFR (7p11.2), and BRAF (7q34)." (PMID 39461959, 2024). "A structure-based computational study against the HeLa cancer cell related protein targets (BCL-2 (4MAN), AKT-1 (4GV1), MCL-1 (5FDO), and BRAF (5VAM)) was used to determine the most potent biomarker." (PMID 40190673, 2024).
cancer (continued). "Recent studies have demonstrated that the combination of BRAF and VEGFR-2 has a mutually reinforcing impact on the proliferation and progression of cancer." (PMID 38999138, 2024). "In conclusion, these genetic findings highlight the importance of understanding the roles of BRAF, ARID2, KMT2C, and GNAQ in different cancer types, shedding light on potential therapeutic targets and predictive markers for cancer treatment strategies." (PMID 38023196, 2023). "The success of kinase inhibitors targeting the MAPK pathway components, such as BRAF and MEK inhibitors, has demonstrated the therapeutic potential of targeting MAPK signaling in cancer." (PMID 37568654, 2023). "Among these potential druggable alterations, EGFR, KRAS, and PIK3CA gene alterations were the most common, while CDK pathway (CDK4/6, CDKN2A/2B), FGFR1/2/3, BRAF, RET was uncommon across pan-cancer." (PMID 36910668, 2023). "Upregulation of ERK/MAPK signaling pathway is a driver mechanism of CRC, whereby cancer progression is warranted by constitutive activation of RAS and BRAF." (PMID 37920169, 2023). "Concerning the mechanism, these inhibitors demonstrate a stronger affinity for both BRAF homodimers and BRAF-CRAF heterodimers, yet they are less effective against CRAF, potentially suggesting reduced impact on KRAS-driven cancers." (PMID 38111008, 2023). "Although neuropilins primarily function as vascular endothelial growth factor (VEGF) coreceptors in cancer, their interactions with CDK4, EGFR, RAS, BRAF, PI3K, and PTEN are not fully understood." (PMID 37885828, 2023). "Molecular characterization of CRC tumors has resulted in the identification of genetic alterations in cancer driver genes, such as KRAS, NRAS, BRAF, and ERBB2, which are now used to guide first‐line therapies." (PMID 37039257, 2023). "In recent years, kinase inhibitors targeting CMGC kinases, such as CDK4/6 inhibitors and BRAF/MEK inhibitors, have demonstrated clinical success in treating specific cancer types." (PMID 37568654, 2023). "HGF from TME has been shown to regulate the innate resistance of BRAF-mutant cancer cells to RAF inhibitors by activating the MAPK and PI3K/Akt signaling pathways in cancer cells." (PMID 37853413, 2023). "The reported prevalence of BRAF and MAP2K1 in-frame deletions in human cancers is thought likely to be an underestimate since sequencing technologies and analytic tools are designed primarily for identification of point mutations." (PMID 37079639, 2023). "Pan-cancer analyses have shown that MYC is the 3rd most frequently amplified gene in malignant neoplasms, and its alterations are mutually exclusive with other genetic drivers like PIK3CA, PTEN, APC or BRAF." (PMID 37443779, 2023). "Small compounds inhibiting SHP2 and PROTACs are being developed, and 11 allosteric SHP2 inhibitors (such as PD-1, MEK, RTK, ERK, BRAF, and ALK) are undergoing clinical evaluation for cancer treatment." (PMID 38001644, 2023). "Using the Alberta Cancer Registry and retrospective chart review, it was determined that roughly three in four CRC patients currently undergo BRAF testing." (PMID 38136294, 2023). "On the other hand, YAPon cancers exhibited increased sensitivity to inhibitors targeting tyrosine kinases (e.g., SRC, ERBB, and EGFR) or serine/threonine kinases (e.g., BRAF)." (PMID 38067201, 2023). "BRAF, on the other hand, is a downstream effector of the RAS/RAF/MEK/ERK signaling pathway, which is frequently activated in many cancers." (PMID 37240450, 2023). "TIS derived from cancer cells treated with targeted inhibitors of EGFR, BRAF, or HER2 signaling unanimously led to an elevated secretome fucosylation." (PMID 36961502, 2023). "The BRAF/PI3K inhibitor effectively suppressed CAF‐mediated drug resistance and decreased cancer invasion." (PMID 36026581, 2022).
cancer (continued). "Overexpressing GLUT1 in KRAS and BRAF mutant cells reportedly results in massive DHA uptake, ultimately leading to ROS production and cancer cell death." (PMID 35915609, 2022). "The existence of targetable oncogenic mutations was excluded by utilizing the Illumina amplicon cancer panel (TSACP), sequencing 212 regions in 48 cancer-related genes including EGFR, BRAF, KRAS, MET, and RET." (PMID 35039644, 2022). "Like the KRAS gene, BRAF is also part of the Ras family that targets the RAS/RAF/MEK/ERK pathway; together, they both account for 7-25% and 5-20% of all cancers as well as 30-45% and 8–10% of CRC for both KRAS and BRAF, respectively." (PMID 35782059, 2022). "Among these patients, about one third or 3.4% of the whole cohort had BRAF and PIK3CA double mutant cancers." (PMID 36079062, 2022). "Both Class 1 and Class 2 BRAF proteins become largely independent from their upstream regulator, RAS GTPase, for growth and proliferation in cancer." (PMID 36077604, 2022). "An epigenetic malfunction is a common event in most cancer, and HDAC inhibitors were shown to synergize with BRAF/MEK/ERK inhibition." (PMID 35936102, 2022). "We selected 17 human cancer cell lines with known mutant genes, such as EGFR, VEGF, BRAF, ALK, and HER2." (PMID 36313330, 2022). "The expression of BRAF and downstream gene (ETS2) was negatively correlated with methylation levels in various cancers." (PMID 35910024, 2022). "According to the available data, dual-targeted therapy with BRAF and MEK inhibition is more advantageous than BRAF inhibitor monotherapy in the treatment of BRAF-mutant cancers." (PMID 36358795, 2022). "Oncoproteins that commonly mutate or genetically alter in cancer cells, including the oncogenic KRAS, oncogenic BRAF, and activated PI3K/AKT, have been shown to result in glucose metabolic reprogramming in cancer cells." (PMID 35163079, 2022). "Some of the most frequently activated oncogenes driving diverse cancers are c-MYC, EGFR, HER2, AKT, KRAS, BRAF, and MEK." (PMID 35594991, 2022). "Customized probes were designed to capture exonic regions of 141 genes selected for the panel, which was aimed for the detection of clinically actionable genetic variations in cancer, including KRAS, NRAS, BRAF, ALK, ROS1, KIT and EGFR." (PMID 35446881, 2022). "For example, BRAF and CDK4, members of the Ser/Thr kinase, up-regulated in cancer, displayed changing connectivity patterns from stages I to IV." (PMID 35448980, 2022). "The most frequent BRAF alteration is V600E, triggering MEK and ERK signaling pathway activation, thus driving cancer progression." (PMID 35326682, 2022). "We observed that the expression of 26 cancer driver genes is downregulated by fb-PMT, representative examples of which include EGFR, NOTCH1/2, MAPK1, CCND1, and BRAF." (PMID 36879662, 2022). "Recent additions to the mCRC armamentarium are the inhibitors of HER2 (rarely overexpressed in CRC, with a higher prevalence in RAS/BRAF–wild type tumors) and NTRK gene fusions (limited to cancers that are wild-type for KRAS, NRAS, and BRAF)." (PMID 36011003, 2022). "Targeting of these oncogenes for cancer therapy is therefore of particular interest, and their specific inhibitors (e.g., erlotinib, vemurafenib, and trametinib, inhibitors of EGFR, BRaf, and MEK, respectively) are currently in clinical use10." (PMID 35831322, 2022).
cancer (continued). "The efficacy of the mTOR inhibitor sirolimus, and targeted therapies that block the Ras/BRAF/MEK/ERK1/2 and PI3KCA/AKT/mTOR pathways in cancer and complex VAs, further supports a role of ESC-like cells in the pathogenesis of these conditions." (PMID 35574555, 2022). "The efficacy of the mTOR inhibitor sirolimus, and targeted therapies that block the Ras/BRAF/MEK/ERK1/2 and PI3KCA/AKT/mTOR pathways in many types of cancer and VAs, further supports the critical role of ESC-like cells in the pathogenesis of these conditions." (PMID 35574555, 2022). "Kynurenic acid seems to be the hub in the metabolite/gene cancer correlation network inferred from CCLE, and several of the cancer genes significantly correlated with metabolites include pan-cancer actors such as MAX, ATM, PTEN, and BRAF." (PMID 35409231, 2022). "Similarly, the cancer-associated BRAF-T121I mutant did not co-localize with SPOP." (PMID 36585710, 2022). "In this work, we systematically evaluated proteome remodeling driven by well-known oncogenes (c-Myc, EGFR, HER2, AKT, KRAS, BRAF, or MEK) expressed in isogenic models and relevant cancer-derived and patient-derived pancreatic cancer and osteosarcoma." (PMID 35594991, 2022). "We found knockdown of BCAT1 significantly reduced the activities of Ras/BRaf/MEK/ERK signalling kinases in SCLC cells, indicating this pathway is involved in BCAT1‐mediated cancer cell proliferation." (PMID 35318805, 2022). "Compared with BRAF mutant/PIK3CA wild type cancers, double mutant cancers were even more often MSI or POLE positive." (PMID 36079062, 2022). "The difference in response rates supports the differing mechanism of action of combined BRAF and MEK inhibitors directly inhibiting cancer cells compared to anti‐PD‐1 immunotherapy altering the host immune system." (PMID 35924450, 2022). "These cell lines showed a spectrum of genetic dependencies on KRAS, HRAS, BRAF, CALM1-3 (the three human CaM genes), the alpha isoform of the C subunit of the PP2A enzyme (PPP2CA) and an endogenous inhibitor of PP2A in cancer, SET." (PMID 35617282, 2022). "Clonality analysis by calculating cancer cell fraction (CCF) revealed that clonal RAS G12, G13, Q61, and BRAF V600E were strictly mutually exclusive with each other (top left cluster)." (PMID 35768438, 2022). "According to the database of COSMIC, the world's largest and most comprehensive resource for exploring the somatic mutations in human cancer, chromosome 7 included lots of well-known cancer-related genes, including EGFR, BRAF, CDK6, MET, T1F1, and so on." (PMID 35568828, 2022). "Given autophagy’s role in the resistance to MAPK inhibition in BRAF mutant tumors, recent attention has turned to the role of autophagy in MAPK therapy resistance in RAS mutant cancers." (PMID 34830283, 2021). "In line with this, the cBioPortal database OncoPrint analysis shows that most of these RTKs have the highest alteration rate, such as EGFR = 10%, ERBB2 = 7%, BRAF = 7%, ROS1 = 5%, and MET = 3%, in 165 (44,752 patients/46,632 samples) cancer cohort studies." (PMID 34769090, 2021). "To study the adaptive changes during targeted inhibition of oncogenic signaling we exposed cancer cells (n = 9) driven by diverse activated kinases (EGFR, MET, BRAF, HER2, ALK) to targeted drugs and performed transcriptional profiling using RNA-seq." (PMID 34535668, 2021). "Drug resistance to targeted drugs including BRAF, MAPK, and MEK signaling pathways in different cancer types affects patient treatment outcomes." (PMID 35003141, 2021). "Although the panRAF inhibitor TAK-632, and the BRAF inhibitors PLX4720 and dabrafenib inhibit BRAF more potently than CCT3833 in in vitro enzyme assays, CCT3833 is more potent at inhibiting KRAS-mutant cancer cell growth, so we examine downstream signaling." (PMID 33130216, 2021).
cancer (continued). "For example nocodazol, a colchicine binding site agent was found to simultaneously inhibit various cancer-related kinases, including ABL1, c-KIT, BRAF, MEK1 (MAP2K1), MEK2 (MAP2K2), and MET." (PMID 33671106, 2021). "Although the role of BRAF, KRAS, and KIT in transcriptomic alterations, tumorigenesis, and progression of several cancers has been partially elucidated, bioinformatics analysis in SKMs has yet to be confirmed." (PMID 34769348, 2021). "CDK4/6is, Palbociclib, Ribociclib and Abemaciclib, have been effectively used in combination therapy, and have shown to be synergistic with drugs targeting other oncogenic pathways, including MEK, KRAS, BRAF, and ALK, in various cancers." (PMID 34138895, 2021). "In solid tumors, the ECM delivered immune evasion signals to cancer cells via integrin, which activated MAP3Ks (TAK1 and BRAF) to phosphorylate ERK." (PMID 34623791, 2021). "Mutations in the WNT (e.g. APC or CTNNB), EGFR (e.g. KRAS, PIK3C or BRAF) and TGF-β (e.g. SMAD4) signalling pathways gradually render cells independent from niche signals to grow autonomously and promoting cancer." (PMID 33594337, 2021). "These class 3 (‘two-hit gain’) drivers include EGFR (2/3 cancer types), KRAS (4/16), and BRAF (1/6)." (PMID 34862370, 2021). "Since MEK mutations are rare in human cancer and MEK1 inhibitors show normal tissue toxicity in cancer therapy, MEK inhibitors are commonly used clinically in combination with BRAF inhibitors." (PMID 34588427, 2021). "Targeting OXPHOS restores the sensitivity of vemurafenib (v-Raf murine sarcoma viral oncogene homolog B (BRAF) inhibitor) - and gefitinib (Epidermal growth factor receptor (EGFR) inhibitor)-resistant cancer cells to the corresponding drugs." (PMID 33673109, 2021). "Adaptive resistance is especially important in BRAF and KRAS mutant cancers, that demonstrate reactivation of the MAPK signaling pathway." (PMID 34071428, 2021). "The CTD2 data set had a total of 79 unique drugs with sensitivities across 351 cancer cell lines that involve 22 targets, such as EGFR, HDAC1, MTOR, MET, ERBB2, and BRAF." (PMID 33795761, 2021). "The combination of BRAF, CRAF, and ATG7 depletion was most successful in reducing cancer cell viability." (PMID 34830283, 2021). "In cell-based assays, Pz-1 selectively inhibited, in the low nM range, proliferation of cancer cell lines only when positive for RET or TRK-derived oncogenes, with negligible effects in cells carrying different driver oncogenes (RAS, BRAF, EGFR)." (PMID 34373541, 2021). "Another important aspect is alterations present in different cancer types with the potential of favorable responses in many patients, illustrated in our study by a large number of studies of ERBB2 and BRAF inhibitors." (PMID 35008297, 2021). "Of these, BRAF harbored an OncoKB level 1 designation, indicating its status as a predictive biomarker of response to an FDA-approved drug in certain cancers." (PMID 34504233, 2021). "BRAF and RAF fusion is a result of chromosomal rearrangement events and is detected in distinct cancer types." (PMID 34625017, 2021). "Although gain-of-function mutations of KRAS and BRAF have been identified as a contributor to SHP099 resistance, more than 77.4% (233/301) of all cancer cell lines with the wild types of both KRAS and BRAF were resistant to SHP099 treatment." (PMID 34790119, 2021). "In contrast, regions more H3K9ac-enriched in HeLa contained genes involved in cell–cell adherens junction (FE 2.0, P = 9.4 × 10–20) and pathways in cancer (FE 1.5, P = 9.9 × 10–8), including oncogenes such as ERBB2, WNT5A and BRAF." (PMID 33542322, 2021). "The mRNA expression of KRAS, BRAF, and KIT in various types of cancer from TCGA samples were analyzed using the UALCAN database (Figure A1 and Figure A2 in Appendix A)." (PMID 34769348, 2021).